TLR1 (toll like receptor 1)
Diseases named in the same sentence as TLR1 in open-access papers (continued):
Sharing a sentence is not in itself a finding about the gene and the disease.
COVID-19 (16 papers, 2021 to 2025). A disease caused by infection with severe acute respiratory syndrome coronavirus 2. "Studies of innate activation unrelated to COVID-19 are also very limited, revealing TLR1, TLR2, TLR3, TLR4, TLR7 and TLR8 activation." (PMID 36769320, 2023). "Severe COVID-19, however, is characterized by additional activation of TLR1, TLR2, TLR4, TLR5, TLR6, NOD1 and NOD2, which are primarily responsive to bacterial antigens." (PMID 36769320, 2023). "Several TLRs (TLR1, TLR2, TLR4, etc.)have an association with disease progression in patients with COVID-19." (PMID 37158916, 2023). "Recent studies demonstrated the involvement of TLR1, 2, and 6 in COVID-19-related cytokine storms by targeting the envelope protein." (PMID 35214676, 2022). "Together, these data suggest an association of MyD88 and a panel of TLRs (i.e., TLR1, TLR2, TLR4, TLR5, TLR8, and TLR9) with disease progression in patients with COVID-19." (PMID 35682644, 2022). "Thus, it could be hypothesized that the upregulation in TLR downstream signaling molecules could be due to increased TLR/MyD88/NF-kB pathway in COVID-19 patients, of which TLR1 and 6 may participate through activation caused by beta-defensin-3, HMGB1 and S protein oligomannose-type glycans." (PMID 33498183, 2021). "Our results suggest that the TLR1, TLR4, TLR6, and TLR10 variants may influence the outcome during corticoid treatment in COVID-19 patients." (PMID 40149530, 2025). "We noted that TLR1 in monocytes also increased with the severity of COVID-19." (PMID 37310504, 2023). "The recent discovery of MMG11 (a TLR2 inhibitor, which shows preference for the TLR1/2 heterodimer) and CuCpt22 (a TLR1/2 heterodimer inhibitor in mice and a TLR1/2/6 inhibitor in humans) may represent potential COVID-19 therapeutics." (PMID 33498183, 2021). "However, increased levels of TLR2 with either TLR1 or TLR6 DAMPs, including beta-defensin-3, named TLR1/2, and the high-mobility group box-1 (HMGB1), named TLR1/2/6, were recorded in peripheral blood mononuclear cells and serum obtained from COVID-19 patients." (PMID 34770863, 2021). "To evaluate the functionality of the innate immune cells in COVID-19, we performed ex vivo stimulation of whole blood with different pathogen-associated molecular patterns (PAMPs): bacterial LPS, a TLR4 ligand; R848, a synthetic ligand for TLR7/8; and Pam3CSK4 (PAM), a synthetic ligand for TLR1/2." (PMID 35380990, 2022). "The highest expression levels are found for Cathepsin L, followed by TLR4/MD-2 and TLR2 on macrophages and endothelial cells, whereas ~10fold lower expression levels are seen for TLR1, 6, and 7, which may correlate with the different pathophysiological relevance in COVID-19, as discussed later." (PMID 35682644, 2022). "Consequently, TLR1/2/6 activation and its consequent signal transduction may play a role in explaining the immunopathological symptoms observed by COVID-19 patients in clinical settings." (PMID 34770863, 2021). "The TLR-1/TLR-2 heterodimer binding SARS-CoV-2 S protein contributes to the inflammatory state and lung injury seen in COVID-19." (PMID 39456843, 2024). "In the case of COVID-19, innate immunity detects SARS-CoV-2 through pattern-recognition receptors (TLR1, TLR4, and TLR6) and activates downstream cascades to initiate viral clearance." (PMID 36833234, 2023). "Proteomic analysis showed changes in signal pathways including JAK-STAT signaling, toll-like receptor TLR1/TLR2 cascade, NFκB phosphorylation, activation of IKKs complex and MHC class II antigen presentation in the COVID-19 brains." (PMID 36609561, 2023). "Parallel to the expression of MyD88, the expression of TLR1, TLR2, TLR4, TLR5, TLR8 and TLR9 was significantly elevated in patients with severe and critical COVID-19." (PMID 35682644, 2022). "Our study suggests that L-pampo, a combination of TLR1/2 and TLR3 agonists, can be a potent adjuvant system for subunit vaccines against COVID-19." (PMID 34579194, 2021).
COVID-19 (continued). "Thus, TLR1/2/6 activation and subsequent signal transduction may be in part responsible for clinical immunopathological manifestations experienced by patients infected with COVID-19." (PMID 33498183, 2021). "In addition, the expression of TLR1, TLR4, TLR5, and TLR8 was significantly elevated in patients with severe or critical COVID-19, and the expression of TLR7 was increased in patients with moderate or critical COVID-19." (PMID 37310504, 2023). "In the current study, we report that the levels of TLR1/2-MyD88 signaling components, the NF-κB complex, and IRF1 were significantly increased as a function of the severity of COVID-19, and the results were consistent with expression levels of IL27 subunits in COVID-19 patients." (PMID 37310504, 2023). "TLR1, TLR4, TLR5, TLR8, and TLR9 expression levels were also significantly elevated in severe and critical COVID-19 patients; however, TLR3 expression was not correlated with the development of COVID-19, and an increased expression of TLR7 was observed only in patients with moderate COVID-19." (PMID 34835108, 2021). "However, elevated levels of TLR1/2/6 DAMPs, including beta-defensin-3 (identified by TLR1/2) and high-mobility group box-1 (HMGB1) (identified by TLR1/2/6), have been reported in peripheral blood mononuclear cells and serum collected from COVID-19 patients, respectively." (PMID 33498183, 2021).
malaria (16 papers, 2009 to 2025). Malaria is a serious and sometimes fatal disease caused by a parasite that commonly infects a certain type of mosquito which feeds on humans. "Another interesting observation reported in Asian patients having acute febrile malaria demonstrates the presence of polymorphisms (rs5743551) on G allele of TLR1 leading to reduced parasitemia and thereby a host directed control on severity of the disease." (PMID 36312954, 2022). "In humans, genetic variation in TLR1 gene is known to influence the parasite burden during malaria caused by Plasmodium falciparum." (PMID 32466538, 2020). "The variant TLR1 I602S was associated with the development of symptomatic malaria and high parasitemia in P. falciparum malaria (Pf-malaria)." (PMID 28850598, 2017). "The current study is the first to document an association of TLR1 rs5743551 with a clinical outcome in an Asian population with malaria." (PMID 26738805, 2016). "However, taken together, these studies suggest that genetic variation in TLR1 affects host susceptibility to malaria disease severity, while variation in TLR6 is less likely to play a significant role in these processes." (PMID 26738805, 2016). "Stronger evidence that TLR1 rs5743551 may influence host responses to malaria is provided by the finding of a significant association between the copy number of the T allele of this polymorphism and increased parasitaemia measured on day 0 of enrollment." (PMID 26738805, 2016). "It was determined that TLR1 polymorphisms previously demonstrated to be associated with functional changes in immunologic signaling were associated with different levels of host control of P. falciparum in patients with clinical malaria." (PMID 26738805, 2016). "Variants in TLR1 may predispose patients with Pf-malaria complications and increased parasitemia." (PMID 28850598, 2017). "This study aimed to evaluate the association between polymorphisms in TLR1, TLR4, TLR7, TLR8, TLR9 and TIRAP and the clinical manifestations of malaria caused by P. vivax in a population from the Amazon region of Pará, Brazil." (PMID 40963451, 2025). "Malaria is an infectious disease that also requires TLR1/2, TLR4, and TLR6 to form an immune response." (PMID 36313452, 2022). "An association of polymorphisms in TLR1 and TLR6 with mild malaria in patients infected with different Plasmodium species was recently demonstrated." (PMID 28850598, 2017). "Therefore, this study aimed to analyse the potential influence of variants of TLR1, TLR4, TLR7, TLR8, TLR9 and TIRAP on the clinical manifestations of malaria caused by P. vivax in the Amazon region of Brazil." (PMID 40963451, 2025). "From an evolutionary thinking, this points to the possibility that G allele of TLR1 rs5743551 occurs in higher frequencies in non-Caucasian hosts and imparts a fitness advantage in malaria endemic zones." (PMID 36312954, 2022). "In addition, SNPs I602S (TLR1) and S249P (TLR6) were associated with severe malaria in Indian patients, showing the genetic contribution of these variants to the onset of cerebral malaria." (PMID 28850598, 2017). "Given the likelihood that associations between TLR1 or TLR6 genotype frequencies and malaria phenotypes would be confounded by major underlying population differences in genetic architecture, analyses for the Karen subjects were performed separately from the other ethnic groups." (PMID 26738805, 2016). "Genetic variation in TLR1 and TLR6 could alter the risk of development of complicated malaria and ability of the host to control the parasite burden during acute Plasmodium falciparum infection." (PMID 26738805, 2016). "Given the potential role of TLR1 in inflammatory responses to malaria, it was hypothesized that the presence of the minor TLR1A7202G allele would be associated with malaria severity and the magnitude of parasitaemia." (PMID 26738805, 2016).
malaria (continued). "Our data demonstrate the first evidence that polymorphisms inIL17 may be associated with uncomplicated malaria in the Cameroonian population while SNPs in, IL10 IL17RD, IRF1, TLR1 and TLR9 may be linked with severe malaria." (PMID 24312262, 2013). "Functional genetic variation within TLR1 and TLR6 could therefore be associated with severity of malarial illness and/or the degree of parasitaemia observed in each patient on the day patients were diagnosed with clinical malaria." (PMID 26738805, 2016). "We show that CD16+ DCs respond to TLR1/2 and TLR4 stimulation with robust TNF production both before and during induced blood-stage malaria." (PMID 30239833, 2019). "From an evolutionary standpoint, this suggests that G allele of TLR1 rs5743551 may persist in higher frequencies in non-Caucasian populations because of a beneficial effect on host fitness in environments with high prevalence of malaria." (PMID 26738805, 2016). "TLR1, TLR2, TLR4, TLR6, TLR7 and TLR9 have been reported to recognize malaria ligands." (PMID 33344264, 2020). "Notably, complement genes (C1QA, C1QB, C1QC), apoptotic genes (PDL1, PDL2, APOL1, APOL2, FAS), inflammatory caspases (CASP1, CASP5), TLR pathway genes (TLR1, TLR4, TLR5, TLR8), cytokines (IL6, IL10), and granzyme (GZMB) were among the genes upregulated during symptomatic malaria." (PMID 39161730, 2024).
viral infection (16 papers, 2010 to 2026). "Mainly four TLRs (TLR-3,4,7, and 8) broadly act as viral antigenic receptors and play a crucial role against viral infections whereas TLR-1,2,5,6,9–12 primarily work against bacterial infection." (PMID 36726141, 2023). "As mentioned in the introduction, the interaction of VTC3 with TLR1/2 is important for the immune response for viral infection; hence docking results further confirm it." (PMID 33828922, 2021). "In this study, we focused on TLR1, TLR2, TLR4, TLR5, TLR6 and TLR9 expression fold changes in two genital epithelial cells (HEC-1-A and VK2) after viral infection." (PMID 30419930, 2018). "Among the TLRs recognizing bacterial patterns, TLR1, 2 and 4 were expressed strongest, whereas TLR8 as a sensor of viral infections showed highest expression of the RNA-responsive receptors." (PMID 20843333, 2010). "The decrease seen in expression of Sf9 tlr1 mRNA after virus infection is consistent with the lack of secretion of DSP-PP240 processing activity by 3 days after viral infection." (PMID 22815932, 2012). "Stimulation of MDMs with the TLR1/TLR2 agonist (mimicking bacterial infection) resulted in a strong increase of CD127 expression, comparable to that after LPS exposure, whereas no relevant induction of CD127 was observed after stimulation with the TLR3 agonist (mimicking viral infection)." (PMID 33584648, 2020). "Interestingly, infection with both viruses markedly promoted the expression of TLR1 and TLR2, which are sensors of bacterial components, which may be explained by the up-regulation of IFNα and IFNγ that could enhance the expression of TLR1, TLR2, TLR3, and TLR7 in viral infections." (PMID 27916934, 2016).
lung carcinoma (12 papers, 2013 to 2025). "However, an opposite correlation was found by other groups who showed that TLR1/2 expression and activation were associated with better prognosis in lung cancer patients, which was further confirmed in mouse lung cancer and breast cancer models by promoting MDSC differentiation into M1 macrophages." (PMID 36911674, 2023). "Among these, two also associated at nominal significance with ovarian cancer (TLR1 and PDCD6), one also associated with lung cancer (POGLUT3) and one associated with each kidney (POGLUT3), and bladder cancer (LAYN)." (PMID 38684708, 2024). "One study showed that miR-16 can enhance radiation sensitivity by regulating the TLR1/NF-κB signaling pathway and act as a potential therapeutic approach to overcome radioresistance for lung cancer treatment." (PMID 33317198, 2020). "One of few TLR1 studies in lung cancer demonstrated miR15a/16 inhibits TLR1 leading to some inhibition of lung tumor xenografts, supporting a role for TLR1 in lung cancer development." (PMID 29190881, 2017). "Based on the limited number of cancer studies on TLR1 and TLR2, it appears that their modulation is cancer-type dependent, with a pro-tumoral role in CRC, gastric and ovarian tumors and an anti-tumoral role in melanoma and lung cancer." (PMID 37112730, 2023). "Both TLR1 and TLR2 have good prognoses for lung cancer and higher expression of these proteins may emerge as useful biomarkers in predicting the outcome or progression of lung cancer." (PMID 36389785, 2022).
Lyme disease (12 papers, 2011 to 2025). Lyme disease (named after the towns in the USA where the disease was first identified) is a bacterial infection caused by Borrelia burgdorferi. "The association of the TLR1-1805GG genotype with excessive inflammation and post-infectious LA provides an example of this concept in Lyme disease." (PMID 41333458, 2025). "In our initial investigation of TLR1, TLR2, and TLR5 variants in Lyme disease, we found that patients with post-infectious LA had a greater frequency of TLR1-1805GG (62%) compared to patients with antibiotic-responsive LA (47%)." (PMID 41333458, 2025). "On the other hand, these results give novel information regarding the mechanisms of Borrelia recognition and the role of TLR1 in this process, and warrants future studies in the role of this receptor for the susceptibility to Lyme disease." (PMID 21998742, 2011). "Finally, TLR1-1805G SNP is likely one of many host risk factors associated with severe Lyme disease." (PMID 41333458, 2025). "The distinct patterns of pro-inflammatory mediator production, along with TLR2/TLR1 expression, and regulation in macrophages from Lyme disease-resistant and -susceptible mice suggests itself as a blueprint to further investigate differential pathogenesis of Lyme disease." (PMID 23024745, 2012). "Despite these limitations, these data support a link between TLR1–1805GG SNP, maladaptive Th1 immunity, and disadvantageous clinical outcomes in several manifestations of Lyme borreliosis, including LNB." (PMID 35318928, 2022). "We previously demonstrated that a SNP (1805GG) in TLR1, a major sensor for Borrelia, alters host immune responses to infection and thereby the clinical course and outcome of Lyme borreliosis." (PMID 35318928, 2022). "In particular the triacylated lipopeptide outer surface protein A (OspA) of Borrelia burgdorferi, which is a TLR-1/2 agonist, has been previously clinically used as a vaccine against Lyme disease with minor side effects." (PMID 24156240, 2013). "However, TLR knockout and overexpression studies have confirmed that lipoproteins drive inflammation in syphilis and Lyme disease through TLR-dependent (TLR1, TLR2) responses." (PMID 25071771, 2014). "Collectively, these data suggest that the TLR1-1805GG variant is associated with excessive immune responses and, as a result, greater disease severity in Lyme arthritis, rather than with overall susceptibility to Lyme disease." (PMID 41333458, 2025). "Our observed TLR2/TLR1 imbalance/dysregulation is not unique to the mouse model of Lyme disease." (PMID 23024745, 2012).
allergic disease (11 papers, 2015 to 2024). An immune response that occurs following re-exposure to an innocuous antigen, and that requires the presence of existing antibodies against that antigen. "In this study, through phenotype screening, we found that TLR1 (rs5743618) is associated with allergic diseases, breast cancer, and the positivity rate of Helicobacter pylori in serum." (PMID 38573314, 2024). "These were attributed to disease-risk loci including loci in or near NOS2 (psoriasis), TLR1 (eczema and allergic disease phenotypes), and FADS2 (vitiligo)." (PMID 39137780, 2024). "SNPs in the TLR1 locus have previously been associated with allergic disease in a number of large meta-GWAS and in a Swedish replication study." (PMID 28228119, 2017). "First, rs17616434 (P = 0.002) was associated with CMA and is located near a cluster of toll like receptor (TLR1, 6, 10) genes, which has earlier been associated with allergic disease." (PMID 26941931, 2015). "Furthermore, analysis to find the association between DNA methylation of the promoter of TLR1 and susceptibility to allergy and influenza was investigated." (PMID 31454983, 2019). "The association of breastfeeding duration (not DNA methylation of the promoter of TLR1) with susceptibility to influenza indicates that breastfeeding may have multiple mechanisms other than the methylation of TLR1 to reduce the susceptibility to both allergy and influenza." (PMID 31454983, 2019). "Secondly, genetic protection against allergy was related to higher cytokine responses to TLR2 ligands through the TLR1-6-10 locus." (PMID 38714679, 2024). "Among these, the increased levels of TNFAIP3, ERBB3, TLR1, and IL1RL2 proteins were associated with a reduced risk of allergic diseases, with corresponding odds ratios of 0.82 (0.76–0.88), 0.74 (0.66–0.82), 0.49 (0.45–0.55), and 0.81 (0.75–0.87), respectively." (PMID 38573314, 2024). "Specifically, elevated levels of TNFAIP3, ERBB3, TLR1, and IL1RL2 proteins were associated with a reduced risk of allergic diseases, yielding corresponding odds ratios of 0.82 (0.76–0.88), 0.74 (0.66–0.82), 0.49 (0.45–0.55), and 0.81 (0.75–0.87), respectively." (PMID 38573314, 2024). "Specifically, we observed associations of genetic instruments for TLR1 and PARK7 with certain allergic diseases such as allergic asthma, allergic rhinitis, and eczema." (PMID 38887235, 2024). "Therefore, we think that TLR1 may be expected to be a therapeutic target for allergic diseases." (PMID 38573314, 2024). "However, it is not clear whether TLR1 plays a role in allergic diseases and the possible mechanisms involved." (PMID 38573314, 2024).